HNRNPU (heterogeneous nuclear ribonucleoprotein U)
Diseases named in the same sentence as HNRNPU in open-access papers (continued):
Sharing a sentence is not in itself a finding about the gene and the disease.
tumor (35 papers, 2014 to 2026). "Future studies incorporating single-cell proteomics and spatially resolved proteomics will further enhance our understanding of the dynamic interactions between TRIM9, HNRNPU, and other tumor-associated factors." (PMID 41050689, 2025). "In this study, we identified TRIM9 as a critical player in regulating the stability of HNRNPU, a key RNA-binding protein involved in tumor progression, via K11-linked ubiquitination." (PMID 41050689, 2025). "hnRNPU interacts with CTCF resulting in transcriptional alteration of genes associated with tumor progression." (PMID 35954396, 2022). "In NB cells, hnRNPU interacts with CTCF resulting in transcriptional alteration of genes associated with tumor progression." (PMID 35954396, 2022). "Furthermore, high hnRNPU expression was associated with advanced tumor stages and correlated with poor prognosis." (PMID 39773744, 2025). "Moreover, FAM171B enhances CCL2 mRNA splicing by interacting with HNRNPU, ultimately resulted in the recruitment of tumor-associated macrophages (TAMs) and their polarization towards the M2 phenotype." (PMID 37915048, 2023). "Compared to its upregulation in tumor cells, the downregulation of HNRNPU in immune cells may also be associated with cisplatin resistance." (PMID 35130920, 2022). "Our analysis revealed a significant reduction in the m6A modification levels of hnRNPU within the tumor tissues compared to the adjacent tissues." (PMID 39773744, 2025). "IHC results revealed that hnRNPU protein levels were higher in tumor versus unpaired normal GC tissues." (PMID 39773744, 2025). "The results indicated that tumor size, weight, and tumor volume decreased upon knocking down hnRNPU." (PMID 39773744, 2025). "Further in vivo experiments demonstrated that overexpression of TRIM9 reduced the tumor volume and weight in nude mice, while co-overexpression of HNRNPU rescued this effect." (PMID 41050689, 2025). "Integrated analyses highlight TRIM9 as a tumor suppressor and prognostic biomarker, mediated via ubiquitination-dependent regulation of HNRNPU stability." (PMID 41050689, 2025). "We analyzed AS events in various tumor samples and identified hnRNPU as a key splicing factor in GC." (PMID 39773744, 2025). "HNRNPU is highly expressed in most tumors, and several studies have indicated that HNRNPU promotes tumor progression through alternative splicing." (PMID 37915048, 2023). "The results of the chemotaxis assays demonstrated that FAM171B overexpression enhanced the chemotaxis of macrophages towards tumor cells in the coculture system, while HNRNPU knockdown and CCR2 inhibition partially attenuated this effect." (PMID 37915048, 2023). "Data from The Cancer Genome Atlas (TCGA) demonstrated that HNRNPU expression was significantly higher in tumor tissues than in normal tissues." (PMID 35130920, 2022). "We found that the expression of HNRNPU in our cohort was significantly upregulated as compared with non-tumor adjacent tissues (p < 0.001)." (PMID 36242708, 2022). "After 28 days of cultivation, tumours were dissected and analysed, and the results showed that tumours in the HNRNPU KO group were significantly smaller than those in the control group." (PMID 36347834, 2022). "We found that RUVBL1 and HNRNPU proteins and mRNA levels were higher in tumor tissues as compared to adjacent/normal tissues." (PMID 36242708, 2022). "We found that the protein HNRNPU is the most positively correlated with the pathological status of Tumor, and the logistic regression result showed that the area under the receiver operating characteristic curve (ROC) is 0.98." (PMID 34895137, 2021). "To verify whether the regulatory function of hnRNPU is modulated by m6A modifications, we collected tumor tissue and adjacent tissue specimens from 7 GC patients and assessed their respective m6A modification of hnRNPU levels." (PMID 39773744, 2025).
tumor (continued). "Additionally, hnRNPU was upregulated in GC with greater lymph node involvement, larger tumor size, and more advanced clinical stage." (PMID 39773744, 2025). "In vivo, TRIM9 overexpression reduced tumor growth, rescued by HNRNPU co-expression." (PMID 41050689, 2025). "Moreover, the integration of single-cell RNA sequencing and spatial transcriptomics in our study provided valuable insights into the cellular heterogeneity and spatial distribution of TRIM9 and HNRNPU within the tumor microenvironment." (PMID 41050689, 2025). "HNF4A-AS1 binds to heterogeneous nuclear ribonucleoprotein U (hnRNPU) to promote its association with CCCTC-binding factor (CTCF), resulting in transactivation of CTCF and transcriptional alteration of HNF4A and other genes associated with tumor progression." (PMID 36923440, 2023). "Owing to the classical regulatory processes happening at gene promoter regions, we hypothesized that certain tumor-specific protein molecules bound specifically to the hnRNPU promoter to downregulate the DNA methylation." (PMID 35875075, 2022). "Given the cited reports related to NSCLC, HNRNPU may be expected to act as a tumor suppressor; however, there is also evidence that supports its pro-tumor effect in different tumor types." (PMID 36242708, 2022). "In the protein data set, the protein HNRNPU is the most positively correlated with the pathological status of Tumor, and the corresponding area under the ROC curve (AUC) score is 0.98 using a logistic regression model for tumor prediction." (PMID 34895137, 2021). "Despite the disparity in sample sizes within the HPA database, which includes 10 normal samples and 100 tumor samples, we identified HNRNPH1, FUS, and HNRNPU as proteins that are highly expressed in GBM." (PMID 40340965, 2025). "We also analyzed the differences in the expression of nomogram model genes (HMGCS2, HNRNPU, RAN) across clinical pathological factors (T, N, M staging, normal vs. tumor)." (PMID 39453509, 2024). "We analyzed the differences in the expression of nomogram model genes (HMGCS2, HNRNPU, RAN) with regard to clinical pathological factors (T, N, M, normal vs. tumor)." (PMID 39453509, 2024). "The expression of HNRNPU and RAN was also enhanced in tumor tissues, with the lowest expression observed in normal tissues (p < 0.001)." (PMID 39453509, 2024). "We observed DHX9 and MATR3 (in Tumor A, set 1), HNRNPC and LARP1 (in Tumor A, set 2), SRSF1 (in Tumor B, set 1 & Tumor B, set 2), SRSF6 and IGF2BP2 (Tumor B, set 2), HNRNPU (in Tumor B, set 2 & Tumor C, set 2), and FAM120A and HNRNPA2B1 (in Tumor C, set 2)." (PMID 31892958, 2020). "Here, we identify heterogeneous nuclear ribonucleoprotein U (HNRNPU) as a novel non-histone substrate of lysine lactylation that links lactate accumulation to serine metabolism and tumor progression." (PMID 42201673, 2026). "Furthermore, the lncRNA CDKN2BAS/miR-153–5p/ARHGAP18 and RP11-386G11.10/miR-345–3p/HNRNPU networks, upregulated in HCC tissues, correlated with larger tumor size, advanced TNM stage, and poorer prognosis in patients." (PMID 38357004, 2024). "Clustering of tumour and healthy lung samples in a 2D map using t-SNE algorithm based on the normalized expression levels of XIST, TSIX, hnRNPu, Bcl-2, and BRCA1, revealed that collectively these five genes -when assessed together- can have a diagnostic potential in both LUAD and LUSC." (PMID 33255394, 2020).
neurodevelopmental disorder (9 papers, 2023 to 2026). A behavioral and cognitive disorder with onset during the developmental period that involves impaired or aberrant development of intellectual, motor, or social functions. "Pathogenic genetic variants of HNRNPU cause a severe neurodevelopmental disorder (NDD), but the underlying molecular mechanisms are unclear." (PMID 41674383, 2026). "We applied a next generation sequencing based assay (EPIC-NGS) to investigate genome-wide methylation profiling for >2 M CpGs for 7 individuals with a neurodevelopmental disorder associated with HNRNPU germline pathogenic loss-of-function variants." (PMID 37407733, 2023). "Furthermore, haploinsufficiency of the most downregulated gene in the subiculum, Mef2c, is associated with a neurodevelopmental disorder showing significant phenotypic overlap to patients with HNRNPU mutations." (PMID 37782669, 2023). "HNRNPU is just one of hundreds of genes that may cause a neurodevelopmental disorder through widespread perturbation of the transcriptome and alternative genetic disorders may have more stable transcriptomic signatures." (PMID 36594023, 2023). "Group 1—Severe multisystem neurodevelopmental disorders (Transcriptional/RNA-processing phenotype): This group included patients carrying variants in POLR1C, TCF4, HNRNPU, NIPBL, and ACTG1." (PMID 41300846, 2025). "Genetic variants affecting Heterogeneous Nuclear Ribonucleoprotein U (HNRNPU) have been identified in several neurodevelopmental disorders (NDDs)." (PMID 37815090, 2023). "Species-specific transcriptomic differences are likely to exist between humans and mice for all transcriptional regulators involved in neurodevelopmental disorders, including hnRNPU, given highly distinct developmental timelines and brain complexity." (PMID 36594023, 2023).
infection (8 papers, 2020 to 2025). The state of being infected such as from the introduction of a foreign agent such as serum, vaccine, antigenic substance or organism. "Previous studies have reported that hnRNPC protein was involved in the infection of hepatitis delta virus (HDV), dengue virus (DENV), Japanese encephalitis virus (JEV), and hnRNPU protein functioned as a nuclear sensor for viral RNA." (PMID 32582087, 2020).
neurologic disease (2 papers, 2018 to 2023). "Protein levels of hnRNPU were increased in many ALS samples compared to non-neurologic disease controls in both cerebellum and spinal cord, mirroring increases observed by IHC in spinal cord." (PMID 29134320, 2018). "The top-ranked RBP, hnRNPU co-localized to cytoplasmic TDP-43 positive inclusions and showed significant protein increases in motor neurons, as well as in cerebellum and spinal cord protein lysates from ALS compared to non-neurologic disease controls." (PMID 29134320, 2018).
brain disorder (1 paper, 2022). A disease affecting the brain or part of the brain. "HNRNPU is an RNA splicing protein associated with brain disorders such as early onset seizures." (PMID 35864088, 2022).
HNRNPU also shares sentences with these, for which no sentence is quoted: viral infections (5 papers); hyperlipidemia (3); cervical cancer (2); colorectal cancer (2); lung adenocarcinoma (2); prostate carcinoma (2); renal cell carcinoma (2); absence seizures (1); acute myeloid leukemia (1); adenocarcinoma (1); autism spectrum disorder (1); cardiomyopathies (1); cardiovascular disease (1); ciliopathies (1); clear cell renal cell carcinoma (1); colon polyps (1); developmental and epileptic encephalopathy (1); encephalopathies (1); esophageal squamous cell carcinoma (1); Fanconi anemia (1); frontotemporal dementia (1); genetic disorders (1); heart failure (1); Hepatic steatosis (1); hereditary leiomyomatosis (1); HIV-1 infection (1); Insulin resistance (1); intestinal cancer (1); left ventricular noncompaction (1); lung squamous cell carcinoma (1).
A further 22 diseases each share a sentence with HNRNPU in 1 paper.